ARMC8 (armadillo repeat containing 8)
Description:
Component of the CTLH E3 ubiquitin-protein ligase complex that selectively accepts ubiquitin from UBE2H and mediates ubiquitination and subsequent proteasomal degradation of the transcription factor HBP1.
Synonyms: S863-2; HSPC056; DKFZP434A043; GID5; VID28
Tractability: Antibody: its Gene Ontology location is reachable by antibodies, with high confidence. PROTAC: ubiquitination databases record sites on it; its protein half-life has been measured.
Gene: Protein-coding gene on chromosome 3 (138,187,248 to 138,298,384, forward strand). Ensembl gene ENSG00000114098.
Subcellular location: Nucleus; Cytoplasm
Subcellular location (Human Protein Atlas): Nucleoplasm; Cytosol; Vesicles
Pathways (Reactome):
Immune System: Neutrophil degranulation
Metabolism: Regulation of pyruvate metabolism
Gene Ontology:
Molecular function: protein binding
Biological process: proteasome-mediated ubiquitin-dependent protein catabolic process
Cellular component: cytoplasm; cytosol; nucleoplasm; nucleus; ubiquitin ligase complex; extracellular region; GID complex; specific granule lumen; tertiary granule lumen
Genetic constraint (gnomAD): Loss-of-function variants: 12 observed, 61.24 expected, observed/expected ratio (o/e) 0.2, 90% interval 0.12 to 0.32. The upper end of that interval is the gene's LOEUF score, 0.32, which puts it in group 1 of 6, group 1 being the genes least tolerant of losing a copy. Missense variants: 415 observed, 622.28 expected, observed/expected ratio (o/e) 0.67, 90% interval 0.62 to 0.72. Synonymous variants: 211 observed, 220.6 expected, observed/expected ratio (o/e) 0.96, 90% interval 0.85 to 1.07.
Homologues: Orthologues: chimpanzee ARMC8 (100% identical), dog ARMC8 (99% identical), pig ARMC8 (99% identical), mouse Armc8 (99% identical), rat Armc8 (99% identical), guinea pig ARMC8 (99% identical), macaque ARMC8 (98% identical), rabbit ARMC8 (96% identical), tropical clawed frog armc8 (92% identical), zebrafish armc8 (87% identical).
Diseases named in the same sentence as ARMC8 in open-access papers:
ARMC8 is named in the same sentence as 29 diseases in open-access papers, as found by Europe PMC text mining. Sharing a sentence is not in itself a finding about the gene and the disease. The quoted sentences say what the papers report.
breast carcinoma (4 papers, 2019 to 2023). "ARMC8 was reported to contribute to malignancy in ovarian, hepatocellular, colon, breast cancers, and so on." (PMID 37400847, 2023). "ARMC8 plays critical roles in cell proliferation, apoptosis, and differentiation, and has been reported to be a prognostic marker in several malignancies including liver, lung and breast cancers." (PMID 36135194, 2022). "In breast carcinoma where ARMC8 expression was detected mainly in the cytoplasm with occasional membrane immunostaining, infiltrating breast carcinoma showed high expression of ARMC8." (PMID 31885576, 2019). "Results also indicated that elevated expression of ARMC8 may be involved in atypia-to-carcinoma progression of breast carcinoma." (PMID 31885576, 2019).
hepatocellular carcinoma (4 papers, 2019 to 2023). A malignant tumor that arises from hepatocytes. "Knockdown of Armc8 in the hepatocellular carcinoma HepG2 cell line significantly up-regulated the expression levels of E-cadherin, β-catenin and αE-catenin." (PMID 30482882, 2019). "Similar results are also reported about ARMC8 in hepatocellular carcinoma." (PMID 31885576, 2019). "This indicated that ARMC8 could regulate cancer invasion through E-cadherin/catenin complex in addition to the fact that it was proposed as potential cancer marker in hepatocellular carcinoma." (PMID 31885576, 2019).
bladder carcinoma (3 papers, 2019 to 2023). "Silencing of Armc8 inhibited TGF-β-induced epithelial–mesenchymal transduction in bladder carcinoma UMUC3 cells." (PMID 30482882, 2019). "TGF-β1 actions in bladder cancer are also mediated by ARMc8 (Armadillo repeat-containing protein 8)." (PMID 31842336, 2019). "Silencing of ARMC8 inhibited TGF-β-induced EMT in bladder carcinoma UMUC3 cells." (PMID 37400847, 2023).
melanoma (3 papers, 2019 to 2024). A malignant, usually aggressive tumor composed of atypical, neoplastic melanocytes. "It has been reported that ARMC8 is upregulated in malignant melanoma cell lines and is associated with an increased invasiveness of melanoma." (PMID 36135194, 2022).
colon cancer (2 papers, 2019). "In 206 cases of colon cancer and the matched adjacent normal tissue, ARMC8 has been found to be significantly higher in the membrane and cytoplasm of tumor cells in comparison with the adjacent normal tissues." (PMID 31885576, 2019). "In vitro, ARMC8 promoted invasiveness and migration of colon cancer cells and downregulation of its levels had again opposite effects." (PMID 31885576, 2019).
lissencephaly type-1 (2 papers, 2017 to 2021). "Armc8 is also a key component of the CTLH (C-terminal to lissencephaly type-1-like homology motif) complex of mammalian cells, which has been characterized as an FBPase (fructose-1, 6-bisphosphatase)-degrading complex." (PMID 28916650, 2017).
schizophrenia (2 papers, 2015 to 2019). A major psychotic disorder characterized by abnormalities in the perception or expression of reality. "Of these, Plscr4, Armc8, Zbtb38, Rbp1, Zic1, and Trpc1 have been linked to schizophrenia or schizophrenia-related disorders in previous studies." (PMID 31920576, 2019).
colorectal adenocarcinoma (1 paper, 2019). The most common type of colorectal carcinoma. "A molecular interaction between Armc8 with Pkp3 was confirmed by co-immunoprecipitation of the endogenous proteins from human colorectal adenocarcinoma cells SKCO-15." (PMID 30482882, 2019).
cutaneous squamous cell carcinoma (1 paper, 2023). "By activating the Wnt signaling pathway, ARMC8 has been linked to increased invasion in cutaneous squamous cell carcinoma and lung cancer." (PMID 37895248, 2023).
lymph node metastasis (1 paper, 2019). "Further, higher ARMC8 expression was found to be linked to lymph node metastasis and advanced tumor-node-metastasis stages." (PMID 31885576, 2019). "Furthermore, ARMC8 increased expression associated with aggressive disease and directly related to TNM stage, lymph node metastasis, and poor prognosis." (PMID 31885576, 2019).
osteosarcoma (1 paper, 2019). A usually aggressive malignant bone-forming mesenchymal neoplasm, predominantly affecting adolescents and young adults. "Knockdown of ARMC8 significantly inhibited osteosarcoma cell proliferation in vitro, and it also inhibited xenograft tumor growth in vivo." (PMID 31885576, 2019). "ARMC8 silencing inhibited the migration and invasion of osteosarcoma cells as well." (PMID 31885576, 2019).
ovary adenocarcinoma (1 paper, 2019). "Overexpression of Armc8 in the ovary adenocarcinoma SK-OV-3 cells led to increased expression of Snail, and to decreased expression of CCC members." (PMID 30482882, 2019).
prostate carcinoma (1 paper, 2020). A carcinoma that arises from epithelial cells of the prostate gland. "RT-qPCR analysis show that ADAM10, ARMC8, COMMD8, EEA1 and PPM1B were expressed at similar levels in prostate cancer cells transfected with ZBTB38 and control siRNAs suggesting that these genes are not regulated by ZBTB38, but rather co-regulated by a common upstream factor and/or pathway." (PMID 32365491, 2020).
tumor (6 papers, 2014 to 2023). "From luciferase assays, we confirmed that ARMC8 was a novel and direct downstream target gene of miR-455-3p, and that the tumor suppressive role of miR-455-3p was in part reversed due to ARMC8 overexpression." (PMID 37400847, 2023). "We identified ARMC8 and showed that miR-455-3p acted as a direct post-transcriptional modulator of ARMC8 and that miR-455-3p had anti-tumor roles by regulating the ARMC8/Wnt/β-catenin axis in GC." (PMID 37400847, 2023). "Xenograft tumor experiment in nude mice confirmed that METTL3 silencing repressed OS cell proliferation in vivo via the HDAC5/miR-142-5p/ARMC8 axis." (PMID 35396379, 2022). "A growing number of studies related to ARMC8 are focusing on tumorigenesis, particularly tumor metastasis." (PMID 34912852, 2021). "Consequently, miR-455-3p repressed Wnt/β-catenin signaling by binding to ARMC8, thereby exerting tumor inhibition effects." (PMID 37400847, 2023). "MiR-455-3p exerted tumor inhibitory effects in GC by targeting ARMC8." (PMID 37400847, 2023). "ARMC8 is overexpressed in many cancers, and is connected to negative prognoses, lymph node metastasis, and tumor-node-metastasis stages." (PMID 37400847, 2023). "Although Armc8 has not been shown to be directly involved in tumor development, it has been shown to regulate proteasome-dependent degradation of the tumor suppressor, α-catenin." (PMID 24700353, 2014).
cancer (4 papers, 2018 to 2019). A tumor composed of atypical neoplastic, often pleomorphic cells that invade other tissues. "Additional studies are necessary to explore the influence of Armc8 expression on desmosomes in human cancer." (PMID 30482882, 2019). "ARMC8 has been shown to reduce the accumulation of E-cadherin and of α- and β-catenin to promote cell invasiveness in various cancers." (PMID 29995892, 2018). "Lately, several studies postulated different effects of Armc8 on the CCC in human cancers." (PMID 30482882, 2019). "ARMC8 is probably the second most investigated member of the CTLH complex in cancer after RANBP9." (PMID 31885576, 2019). "Degradation of αE-catenin has been reported to be important in cancer and to be regulated by Armc8." (PMID 30482882, 2019).
infection (2 papers, 2016 to 2022). The state of being infected such as from the introduction of a foreign agent such as serum, vaccine, antigenic substance or organism. "Furthermore, there were nine proteins that were specifically detected at 7 days post-infection (Saa2, Trappc1, Cxadr, Armc8, Hbxip; Lamtor5, Prppsap2, Usp46, Pcdh10, Neo1)." (PMID 36061859, 2022).
nervous system disorder (1 paper, 2022). A non-neoplastic or neoplastic disorder that affects the brain, spinal cord, or peripheral nerves. "On the other hand, the ARMC proteins including ARMC4, ARMC5, ARMC6, ARMC7, ARMC8, ARMC10, and ARMCX3 regulate the Wnt signaling pathway leading to specific nervous system disorders." (PMID 36553564, 2022).
ARMC8 also shares sentences with these, for which no sentence is quoted: gastric cancer (2 papers); chronic kidney disease (1); head and neck squamous cell carcinoma (1); Hypertension (1); lung carcinoma (1); myeloproliferative neoplasm (1); non-small cell lung carcinoma (1); ovarian carcinoma (1); pancreatic cancer (1); pulmonary arterial hypertension (1); renal cell carcinoma (1); skin tumor (1).